MTOR (mechanistic target of rapamycin kinase)
Diseases named in the same sentence as MTOR in open-access papers (continued):
Sharing a sentence is not in itself a finding about the gene and the disease.
breast cancer (continued). "Based on mediation of the signals of multiple growth factors, the PI3K/p-AKT/mTOR pathway has been shown to play a pivotal role in breast cancer metastasis and drug resistance." (PMID 32775453, 2020). "Because the PI3K/Akt/mTOR pathway is frequently deregulated in breast cancers, mTORC1 inhibitors have been used in the clinic, but the success of rapalogues has been thwarted due to the activation of Akt involving a negative feedback loop." (PMID 32549199, 2020). "In our previous study, we demonstrated that deficiency in DPP-4 induced EMT in 4T1 cells, MCF-7 cells and MDA-MB-231 cells and accelerated lung metastasis of breast cancer in vivo via the CXCL12/CXCR4/mTOR axis." (PMID 31991851, 2020). "The potential of simultaneously targeting ER, PI3K/mTOR, and CDK4/6 signaling de novo was evaluated in three ER+/HER2− breast cancer xenograft models representing diverse molecular backgrounds of PI3K/mTOR pathway activation." (PMID 32795346, 2020). "Everolimus is an mTOR inhibitor with well-known antitumor activity in advanced cancer, including kidney and breast cancer." (PMID 32883368, 2020). "Aberrations in the PI3K/AKT/mTOR pathway are common genomic abnormalities in the majority of human cancers including breast cancer." (PMID 32391382, 2020). "Previous studies showed that adiponectin can activate AMPK and its downstream effector mTOR in breast cancer through ERα, resulting in a stimulatory effect on the proliferation of breast cancer cells." (PMID 32529777, 2020). "UCA1 induced tamoxifen resistance in breast cancer cells partly through activation of the mTOR pathway." (PMID 31143372, 2019). "In summary, we report here that mTOR-dependent translation of Mcl-1 increases Mcl-1 expression and promotes cell survival in ER+ breast cancer cells." (PMID 31595181, 2019). "Inhibitor of mTOR, such as everolimus, has shown modest clinical activity in ER+ breast cancers when given with an antiestrogen." (PMID 31428575, 2019). "This induced C/EBPδ can suppress FBXW7 in breast cancer, consequently increasing oncogenic mTOR/AKT/S6K1 signaling as well hypoxia-inducible factor-1α (HIF-1α) required for hypoxia adaptation, thereby promoting tumor metastasis." (PMID 30791487, 2019). "The mTORC2, a functional complex of mechanistic target of rapamycin (mTOR) together with the components mTOR, mLST8, Rictor, mSIN1, and Protor1/2, is regarded as apromising target for breast cancer therapy 10-13." (PMID 31595162, 2019). "Intriguingly, PI3K/AKT/mTOR signaling was distinctly activated in breast cancer with high DEPDC1 expression." (PMID 31032225, 2019). "For example, S6 kinase promotes OC cell metastasis, and recent research showed that activation of mTOR/S6K enhanced the proliferation of HER2-breast cancer; S6K also participated in regulating the proliferation of prostate cancer." (PMID 31799599, 2019). "Cellular changes in amino acids such as glutamine are sensed by the mammalian target of rapamycin (mTOR) complex, mTORC1, which is often deregulated in ER+ advanced breast cancer." (PMID 31428575, 2019). "The in vitro assays demonstrated that DEPDC1 promoted the proliferation, migration, and invasion, and involved in PI3K/AKT/mTOR signaling in breast cancer cells." (PMID 31032225, 2019). "A recent study reported that cannabidiol-induced apoptosis of breast cancer cells by downregulation of mTOR and cyclin D1, and upregulation PPARγ." (PMID 31075907, 2019). "Hyperactivation of PI3K/Akt/mTOR pathway has been considered as essential element leading to endocrine therapy resistance in breast cancer." (PMID 31657150, 2019). "For example, the allosteric mTOR inhibitor temsirolimus significantly enhanced the anti-cancer activity of CA4-nanoparticles in a breast cancer model." (PMID 31888052, 2019). "Autophagy can be also mediated by TRPC5 and promotes drug resistance via CaMKKβ/AMPKα/mTOR pathway in breast cancer cells." (PMID 30884858, 2019).
breast cancer (continued). "By contrast, silencing SALL2 induced downregulation of ERα and PTEN and activated the Akt/mTOR signaling, resulting in estrogen‐independent growth and tamoxifen resistance in ERα‐positive breast cancer." (PMID 31657150, 2019). "Phosphorylation of S6K1 (P-S6K1) is a key biomarker of functional mTOR pathway activation and is abnormally expressed in prostate cancer, melanoma, breast cancer, lung cancer and colorectal cancer." (PMID 31799599, 2019). "In breast cancer, quercetin can help preventing relapse by decreasing expression and activation levels of mTOR, PI3K and Akt proteins leading to a significant inhibition of MCF7 cancer cell proliferation." (PMID 31744117, 2019). "Mechanistically, hypermethylation‐mediated SALL2 reduction induced anti‐estrogen resistance by downregulating ERα and promoted hormone‐independent growth by regulation of PTEN/Akt/mTOR signaling cascade in human breast cancer cells." (PMID 31657150, 2019). "Apart from c-Met inhibition, the strong antiproliferative effect of Oc against several breast cancer cell lines and downregulation of the expression of phosphorylated mTOR in metastatic breast cancer cell line was reported." (PMID 31137753, 2019). "In breast cancer, JAK2/STAT5 activation is associated with resistance to PI3K/mTOR inhibitors, and combination therapy targeting JAK2/STAT5 and PI3K/mTOR was proposed to overcome this resistance." (PMID 31601188, 2019). "Alterations of the PI3K/AKT/mTOR pathway belong to the most commonly found molecular changes in human cancers, including breast cancer." (PMID 31835495, 2019). "We previously found that Aur-A activated the mTOR pathway and inhibited autophagy activity in breast cancer cell models." (PMID 31406104, 2019). "Further, the present study provided a novel regulatory mechanism of DEPDC1 in breast cancer by strengthening PI3K/AKT/mTOR signaling to deteriorate phenotypes." (PMID 31032225, 2019). "A hormone receptor is mainly concerned with the progression of the PI3K/AKT/mTOR pathway which is often dysregulated in breast cancer." (PMID 31030499, 2019). "A study by Ke and Lou showed that microRNA-10a, which can downregulate tyrosine kinase, suppressed breast cancer progression through regulating the PI3K/Akt/mTOR pathway." (PMID 31398899, 2019). "MCF-7 breast cancer cells with BRCA1 knockdown were more sensitive to pan-mTOR inhibitor PP242 and pan-PI3K/pan-mTOR inhibitor PKI-179 than cells with the non-targeting scrambled control." (PMID 31771139, 2019). "The PI3K/Akt/mTOR signaling pathway is closely related to the enhancement of autophagy and is always activated in cancers, including breast cancer." (PMID 30897708, 2019). "We evaluated the efficacy of formononetin in improving the tumoricidal effect of everolimus by suppressing the mTOR pathway in breast cancer cells." (PMID 31007702, 2019). "Many researches have focused on effect of PI3K/AKT/mTOR pathway inhibitors in patients suffering from advanced HER2+ breast cancer." (PMID 30975222, 2019). "BITC treated breast cancer cells exhibit FoxO1-mediated autophagy and induces apoptosis via attenuation of mTOR activity in vitro and in vivo." (PMID 31618928, 2019). "Conversely, reducing OGT levels or O-GlcNAcylation in breast cancer cells leads to inhibition of mTOR activity as measured by phosphorylation of ribosomal protein S6 kinase beta-1 (p70S6K), an mTOR target." (PMID 31272438, 2019). "Consistently, QUE was able to reduce the protein levels of MMP-2, MMP-9, VEGF and mTOR, and p-Akt in breast cancer cell lines." (PMID 31261749, 2019). "Deregulation of the mTOR (mammalian target of rapamycin) pathway has been widely reported in TNBCs when compared to ER+/PR+/HER2 overexpressing breast cancers, and is correlated to the poor outcome among TNBC patients." (PMID 30626087, 2019).
breast cancer (continued). "mTOR activity has also been found to have a 24-h rhythmic pattern in cultured breast cancer cells and the efficacy of in vitro everolimus, an mTOR inhibitor, varied depending on the timing of the dose." (PMID 33089179, 2019). "Delphinidin also influences the proliferation of ovarian cancer cells via PI3K/AKT and ERK1/2 MAPK signalling axis Moreover, it was shown that this compound induces autophagy in HER2+ breast cancer cells via inhibition of AKT/mTOR pathway." (PMID 30609679, 2019). "Quercetin also has the ability to induce protective autophagy in gastric and breast cancer cells by inactivating the Akt-mTOR pathway and HIF-1α signaling." (PMID 31261749, 2019). "Everolimus as the inhibitor of mTOR kinase hampers PI3K/Akt/mTOR pathway and returns sensitivity to the endocrine therapy, for instance, in hormone receptor-positive (HR+) breast cancer patients." (PMID 31557936, 2019). "The mTOR pathway is known to play a key role supporting the rapid proliferation of breast cancer cells and therefore we studied the effects of treatment with metformin on the modulation of mTOR and its downstream targets." (PMID 30626087, 2019). "HNK synergistically induces apoptosis in combination with mTOR inhibitor, rapamycin, in breast cancer cells." (PMID 31618928, 2019). "Activation of PI3K/AKT/mTOR signaling contributes to the pathogenesis of many cancer types including breast cancer." (PMID 31277699, 2019). "To evaluate the mechanism of action of TAK228, we assessed its effect on the Akt/mTOR signaling in eight breast cancer cell lines." (PMID 31489111, 2019). "Recent findings in breast cancer, in which the mTOR/Akt/PI3K axis is the most frequently enhanced oncogenic pathway, have suggested a possible synergy for ovarian cancer patients between PI3K inhibitors and poly-adenylate ribose polymerase (PARP) inhibitors." (PMID 31197119, 2019). "Aberrations in the PTEN genes also influence cancer cells in myeloma, breast cancer and endometrium cancer, which are sensitive to mTOR inhibitors." (PMID 30754640, 2019). "Aside from the rapalogs, other mTOR inhibitors, such as ATP competitive inhibitors and PI3K /mTOR dual inhibitors, have also been studied in breast cancer." (PMID 30754640, 2019). "Particularly, about 60% of breast cancer tumors accommodate genetic variations leading to high activity of the PI3K/AKT/mTOR signaling route which have been classified as oncogenic driver mutations." (PMID 31906235, 2019). "mTOR hyperactivity is frequently observed in TNBC compared to other breast cancer subtypes and is often correlated with poor prognosis, underpinning the potential of mTOR-targeted therapy for TNBC treatment." (PMID 31388935, 2019). "Currently, only one drug that targets the PI3K pathway is available for breast cancer treatment, namely everolimus, which is an mTOR inhibitor." (PMID 31404155, 2019). "The activation of PI3K/AKT/mTOR signaling pathway is closely connected with clinical characteristics and poor prognosis in breast cancer." (PMID 31032225, 2019). "When breast cancer patients start to exhibit resistance to hormonal therapy or chemotherapy, the mTOR inhibitor everolimus can be considered as an alternative therapeutic agent." (PMID 31358767, 2019). "Whereas mTOR amplification is rare in human cancer, rictor amplification is detected in various kinds of cancer, such as breast cancer, gastric cancer, and liver cancer." (PMID 31277692, 2019). "The object of BOLERO-2 trial is to evaluating combination of mTOR inhibitor everolimus with aromatase inhibitor (AI) in HR positive advanced breast cancers." (PMID 30754640, 2019). "There is wide recognition that PI3K/AKT/mTOR signaling plays a critical role in many cancer types including breast cancer." (PMID 31277699, 2019). "Our previous research proved that PGC-1β was significantly overexpressed in breast cancer and inhibited the apoptosis of breast cancer cells via mTOR signaling pathway." (PMID 31007610, 2019).
breast cancer (continued). "Previous studies have shown that SNCG promoted the expression of Akt and mTOR as induced cancer growth in human breast cancer." (PMID 31333726, 2019). "Recent findings demonstrated that adiponectin differently regulated the LKB1/AMPK/mTOR signaling in breast cancer cells." (PMID 31052147, 2019). "Other studies have found that PL also exerts its anticancer effects via inhibition of the STAT3 and Akt/mTOR signaling pathways in breast cancer cell lines." (PMID 31739520, 2019). "Out of 40 inhibitors of mTOR against breast cancer, SF1126 was identified to have the best docking score of -8.705, using Schrodinger Suite which was further subjected for high throughput screening to obtain best similar compound using Lipinski’s filters." (PMID 31030499, 2019). "Activation of the PI3K/AKT/mTOR signaling pathway contributed to the resistance to endocrine therapy in breast cancers." (PMID 31905960, 2019). "In another study, the up-regulation of mTOR and its downstream molecules was investigated and it has been revealed that the breast cancer cells are sensitive to the rapamycin." (PMID 31557936, 2019). "In breast cancer, the activation of mTOR is required for CSCs maintenance and viability, and activation of PI3K/Akt, achieved by knocking down PTEN, enriched breast CSCs." (PMID 30635656, 2019). "Contrarily, the finding for the MTOR gene and breast cancer is biologically plausible because the MTOR protein plays an important role in PI3K/Akt signaling, which is a pathway related to cancer development and cell senescence." (PMID 30678711, 2019). "LKB1 is also considered as tumor suppressor that is lost in several cancer types including breast cancer, and it is able to act through several signaling cascades, such as mTOR, AMPK (5' adenosine monophosphate-activated protein kinase) or PI3K/AKT." (PMID 31191821, 2019). "Inhibitors of the mammalian target of rapamycin (mTOR) are approved for immunosuppression post solid organ transplantation and the treatment of mantle cell lymphoma, breast cancer, neuroendocrine tumors and renal cell cancer." (PMID 30700842, 2019). "Possibly due to mistargeted localization and the lack of suitable signalling co-factors on late endosomes, HER2 signalling to the PI3K/AKT/mTOR proliferative pathway was decreased in SORLA-silenced breast cancer cells." (PMID 31138794, 2019). "Following treatment with fisetin, the viability of 4T1, MCF-7, and MDA-MB-231 breast cancer cells was reduced through interfering with the PI3K/Akt/mTOR pathway." (PMID 31064104, 2019). "A combination of honokiol with the mTOR inhibitor rapamycin presented synergistic effects to induce apoptosis in breast cancer cells where the inhibition of PI3K/Akt/mTOR signalling by the mTOR inhibitor further sensitizes breast cancer cells to honokiol." (PMID 31877856, 2019). "Among these pathways, the PI3K/AKT/mTOR signaling cascade has been described as frequently activated in different solid tumors, including up to 60% in breast cancers according to a recent The Cancer Genome Atlas (TCGA) analysis." (PMID 31835495, 2019). "The obtained results signify that liposomal Met has superior apoptotic activity via the AMPK/mTOR pathway in breast cancer cells." (PMID 31661947, 2019). "In the current experimental study, we scrutinized the chemoprotective effect of astraxanthin against the 7,12-dimethylbenz(a)anthracene (DMBA)-induced breast cancer via Nrf-2-Keap1 and NF-kB and mTOR/Maf-1/PTEN pathway." (PMID 31556759, 2019). "The pathway PI3K/AKT/mTOR is frequently activated in breast cancer potentially controlling many major cytophysiologically functions related to cellular proliferation, metastasis, growth, survival and motility." (PMID 31358767, 2019). "FBW7 can be used to target the degradation of the mTOR protein; furthermore, it can promote the degradation of mTOR protein in breast cancer and renal cancer." (PMID 31119177, 2019).
breast cancer (continued). "For example, the mammalian target of rapamycin (mTOR) inhibitor everolimus in combination with exemestane has demonstrated benefit in patients with HR+ advanced breast cancer." (PMID 30949915, 2019). "Visfatin can enhance iNAMPT, eNAMPT, PI3K, and mTOR protein expression and increase breast cancer cell proliferation." (PMID 31817697, 2019). "We report here that blockade of Bcl-2 or Bcl-xL, alone or together, rapidly induced mTOR signaling in ERα+ breast cancer cells, rapidly increasing cap-dependent Mcl-1 translation." (PMID 31595181, 2019). "The main goal of this study was to assess the use of IF as a modality to predict the efficacy of the mTOR inhibitor everolimus alone in breast cancer cells." (PMID 31358767, 2019). "In breast cancer cells, increased mTOR activity is associated with elevation of total O-GlcNAcylation and increased OGT protein levels, while blocking mTOR activity with rapamycin leads to reduced O-GlcNAcylation and OGT levels." (PMID 31272438, 2019). "For breast cancer, mTOR-targeted therapy is considered when patients are resistant to hormonal therapy or chemotherapy." (PMID 31358767, 2019). "It was shown that the levels of PGC-1β and mTOR correlated with overall mitochondrial activity in breast cancer samples." (PMID 31921637, 2019). "The combination of the chemotherapeutic agent PTX, and the mammalian target of rapamycin (mTOR) inhibitor everolimus (EVER) has previously been shown to have pronounced synergistic effects in breast cancer (BC) cells in vitro." (PMID 31146485, 2019). "It has shown anticancer activity on mammary carcinoma cells via regulation of the PI3K/AKT/mTOR pathway." (PMID 30609679, 2019). "Numerous studies have focused on the PI3K/AKT/mTOR pathway in estrogen receptor positive (ER) breast cancer (BC), as a linear signal transduction pathway and reported its association with worse clinical outcomes." (PMID 30729154, 2019). "Previous research has clarified that mir-155 enhances mTOR activity in the progression of breast carcinomas." (PMID 31456816, 2019). "In breast cancer, intracellular glutamine is important for activation of the mTOR pathway via glutaminolysis and induces cancer cell proliferation." (PMID 29562706, 2018). "mTOR inhibitors have found application in treatment for various malignancies like renal cell carcinomas and breast cancers." (PMID 30469530, 2018). "miR-99b targets include mTOR signaling pathway which inhibition has been previously related in breast cancer cells with an increase in autophagy." (PMID 30388154, 2018). "Deregulated PI3K/mTOR signals can promote the growth of breast cancer and contribute to endocrine treatment resistance." (PMID 29128895, 2018). "We tested a number of different targeted drugs (PI3K: alpelisib (BYL719), buparlisib (BKM120) and IPI549; AKT: Ipatasertib (GDC-0068); mTOR: rapamycin) for their effects on T47D breast cancer cells." (PMID 30382095, 2018). "OC-induced apoptosis was more selective against breast cancer cells that highly expressed the mammalian target of rapamycin (mTOR)." (PMID 29734791, 2018). "Of note, both the stroma-intensive expression of Zscan4 in the post-treatment patients and significant correlations between Zscan4 and p38/mTOR were validated through pathological assessment of human breast cancer (BCa) patient samples." (PMID 29712904, 2018). "Consistent with reports in other cancer types 14, we found ADAMTS9 inhibits the AKT/mTOR signalling pathway in breast cancer cells." (PMID 29193730, 2018). "Our data also revealed that the phosphorylation levels of S6K1 at T389 (p-S6K1T389), which is a well-known mTOR phosphorylation site, increased in breast cancer cells with TNFα treatment." (PMID 30154412, 2018). "Because fulvestrant (pure estrogen receptor antagonist)-resistant breast cancer frequently shows the upregulation of mTOR pathway, the combination of fulvestrant and mTOR inhibitor is more efficious than fulvestrant alone." (PMID 30497501, 2018).